ADAM9 (ADAM metallopeptidase domain 9)
Diseases named in the same sentence as ADAM9 in open-access papers (continued):
Sharing a sentence is not in itself a finding about the gene and the disease.
breast carcinoma (30 papers, 2004 to 2026). "However, the ADAM9 splice variants have opposing effects on breast cancer cell migration." (PMID 24705471, 2014). "Silencing ADAM9 by siRNA inhibited the migration of BT-549 breast cancer cells and the invasion of MDA-MB-231 breast cancer cells." (PMID 40214422, 2025). "Together, these findings establish that ADAM9 contributes to breast cancer cell survival via cell death inhibition and radioresistance while contributing to breast cancer cell progression via the promotion of proliferation, migration, and invasion." (PMID 40214422, 2025). "In basal-like breast cancer, we found that a low WWOX/HIF1A ratio is associated with particularly aggressive disease because it promotes EMT via ZEB1 and ADAM9, facilitates ECM remodelling via MMP2 and ITGA1, and enables immune evasion via NOTCH1 and TLR4." (PMID 41007296, 2025). "Among the ADAM isoforms, ADAM9 and ADAM10 have been identified in EVs associated with breast cancer." (PMID 40214422, 2025). "ADAM9 is an adhesive protein and can induce cell signaling, leading to increased proteolytic activities and it is overexpressed in breast cancer and plays an important role in metastasis." (PMID 35954348, 2022). "Further study showed that miR-33a overexpression inhibited metastatic breast cancer cell growth and mobility in vitro and in vivo by targeting ADAM9 and ROS1." (PMID 32206036, 2020). "In breast cancer patients, some ADAMs mRNA expression levels were significantly increased in breast cancer surgically removed samples, including ADAM9 mRNA." (PMID 32875951, 2020). "Breast cancer cell lines and patient specimens were used to evaluate the ADAM9 expression by western blotting and immunohistochemistry staining, respectively." (PMID 32637415, 2020). "Significant upregulation of ADAM9 mRNA was observed in TNBC primary tumor compared to ER+ breast cancer primary tumor from published GEO datasets (GSE58135)." (PMID 32637415, 2020). "Several miRNA expression profiles and target sites on ADAM9 have been studied in breast cancer, including miR-126, miR-154, and miR-33a." (PMID 33096780, 2020). "Based on the data acquired from public databases, the correlation between ADAM9 expression and breast cancer patient survival was analyzed by Kaplan-Meier method." (PMID 32637415, 2020). "In short, this high-level form of ADAM9 is most likely related to the poor prognosis of breast cancer patients." (PMID 32875951, 2020). "In the SNX9 knockdown breast cancer cells, total ADAM9 protein expression and cell surface ADAM9 proteins are elevated, and the protease function of ADAM9 is active in shedding of the ADAM9 substrate EphB4." (PMID 33096780, 2020). "ADAM9 expression of breast cancer cell lines from CCLE showed the same pattern in TNBC cell lines when compared with non-TNBC cell lines." (PMID 32637415, 2020). "On the other hand, the low expression of ADAM9 on tumor cells also impedes the interaction between platelets and tumor cells in breast cancer and melanoma." (PMID 33096780, 2020). "The overexpression of miR-126 significantly reduces the expression level of ADAM9 protein, a key molecule involved in cancer cell metastasis, and thus plays a role in suppressing cell invasion in the development of breast cancer." (PMID 32875951, 2020). "Survival analysis indicated that ADAM9 overexpression was correlated with poorer outcome in patients with breast cancer and TNBC." (PMID 32637415, 2020). "Increasing hazard ratio was found with increasing tumor grades, which indicated the important role of ADAM9 in high grade of breast cancer." (PMID 32637415, 2020). "Compared with normal breast tissue, ADAM9 mRNA is more frequently expressed in breast cancer and fibroadenoma." (PMID 32875951, 2020). "ADAM-8, -12, -15 and -28 are highly expressed in non-small cell lung cancer, ADAM-9, -12, -17 and -23 are highly expressed in breast cancer and ADAM-9, -12 and -17 are highly expressed in liver cancer." (PMID 24465799, 2014).
breast carcinoma (continued). "ADAM9 was increased in breast cancer in comparison with normal breast tissue and correlated positively with HER2 expression." (PMID 24952873, 2014). "Moreover, a mechanistic study revealed that ADAM9 promotes the progression of MDA-MB-231 breast cancer cells by activating the AKT/NF-κB pathway, an oncogenic signaling pathway implicated in many cancers." (PMID 40214422, 2025). "ADAM9, also known as meltrin-γ, was initially identified in breast carcinoma." (PMID 40427200, 2025). "The knockdown of ADAM9 in MDA-MB-231 breast cancer cells inhibits tumour cell invasion in vitro." (PMID 40427200, 2025). "In breast cancer, circNINL and circ_0008784 upregulation could indirectly affect Wnt/β-catenin activation through sponging miR-921 and miR-506–3p to promote ADAM9 and CTNNB1 (catenin beta 1) expression, respectively." (PMID 39524849, 2024). "Circ-ADAM9 is upregulated in breast cancer, and inhibition of circ-ADAM9 could induce breast cancer radiosensitivity and apoptosis by acting as a decoy of miR-383-5p to regulate the level of PFN2." (PMID 38186573, 2023). "We retrieved breast cancer specimens from clinic and investigated their ADAM9 protein expression." (PMID 32637415, 2020). "In breast cancer, the expression of ADAM9 is up-regulated compared to normal tissue." (PMID 33096780, 2020). "In this condition, MCF-10A might have a higher ADAM9 expression than some breast cancer cell lines as a response to additional EGF in cultural medium." (PMID 32637415, 2020). "Furthermore, higher ADAM9 expression correlated with poorer RFS in higher-grade breast cancer in our study." (PMID 32637415, 2020). "HTERT-HME1, another immortalized human breast epithelial cell line cultured with MEGM BulletKit, also has higher ADAM9 expression (normalized expression = 35.2) than some other breast cancer cell lines (MCF-7 = 4, SKBR3 = 17.9 and T47D = 14.5), which is similar with MCF-10A." (PMID 32637415, 2020). "According to the upregulated ADAM9 expression in TNBC cell lines and tumors, we investigated whether upregulated ADAM9 expression is associated with poor prognosis of breast cancer patients, especially in patients of TNBC." (PMID 32637415, 2020). "MiR-33a might inhibit breast cancer cell proliferation and metastasis by suppressing ADAM9 and ROS1." (PMID 26507842, 2015). "One member of this family, ADAM9, is overexpressed in breast cancer." (PMID 26507842, 2015). "The chromosomal region of ADAM9 (8p11–12) is amplified in some breast cancer tumors and cell lines." (PMID 22570691, 2012). "ADAM9, which is important in cell adhesion and tumor cell invasion, has potential in male breast cancer as well, since this gene is often affected and could be used for targeted therapy." (PMID 22527098, 2012). "ADAM9 expression was increased in tumor tissues from TNBC patients and TNBC cells compared with the non-TNBC tumor tissues and cell lines, which is consistent with the previous finding that ADAM9 was overexpressed and associated with a more aggressive phenotype of breast cancer." (PMID 32637415, 2020). "The authors further demonstrated that depletion of ADAM9 impedes growth and increases radiosensitivity and apoptosis of MCF-7 and MDA-MB-231 breast cancer cells." (PMID 40214422, 2025). "ADAM9 (also known as metalloprotease/disintegrin/cysteine-rich protein 9 (MDC9) or meltrin-γ), one of the ADAM proteins, was first identified in 1996 in breast carcinoma." (PMID 33096780, 2020). "The results indicated that high ADAM9 mRNA expression was significantly correlated with poor OS (p < 0.01), DMFS (p < 0.01), and RFS (p < 0.001) in breast cancer patients." (PMID 32637415, 2020). "Taken together, these results indicate that ADAM9 and ROS1 are direct targets of miR-33a in breast cancer cells." (PMID 26507842, 2015).
breast carcinoma (continued). "The ectopic expression of miR-33b downregulated the expression of ADAM9, HMGA2, LDHA, SALL4, SNAI2 and Twist1 by more than 30% but had minimal effects on HIF-1α, RAC1, Yes1 and ZEB1 in these two breast cancer cell lines." (PMID 25919570, 2015). "Moreover, the miR-33a level is inversely associated with the expression of ADAM9 and ROS1 in breast cancer tissues, indicating that miR-33a may inhibit breast cancer cell proliferation and metastasis, at least in part, by downregulating the levels of ADAM9 and ROS1." (PMID 26507842, 2015). "In unsupervised hierarchical clustering a distinctive group of male breast cancer with poor prognosis (p = 0.009; hazard ratio 3.4) was identified, characterized by frequent CCND1, MTDH, CDC6, ADAM9, TRAF4 and MYC copy number gain." (PMID 22527098, 2012). "Consistent with this, ADAM9 and ADAM10 are overexpressed in breast cancer." (PMID 40214422, 2025). "In a large number of breast cancer samples, the expression of ADAM9 protein 84 kDa is higher than that of negative tumors in lymph node positive tumors, and it is positively correlated with HER-2/neu protein levels." (PMID 32875951, 2020). "To determine whether ADAM9 is overexpressed in TNBC primary tumor when compared to non-TNBC primary tumor, we investigated the ADAM9 expression in breast primary tumor and breast cancer cell lines." (PMID 32637415, 2020). "Immunohistochemical staining showed that breast cancer tissues with high miR-33a expression have low expression of ADAM9 and ROS1, whereas breast cancer tissues with low miR-33a expression exhibit high expression of ADAM9 and ROS1." (PMID 26507842, 2015).
melanoma (28 papers, 2008 to 2024). A malignant, usually aggressive tumor composed of atypical, neoplastic melanocytes. "Also, the expression of an ADAM protease, ADAM9, is associated with human melanoma progression." (PMID 35558554, 2022). "It has also been shown that miRNA-126-3p down-regulation contributes to dabrafenib-acquired resistance in melanoma patients by up-regulating ADAM9 (ADAM Metallopeptidase Domain 9) and VEGFA." (PMID 38469304, 2024). "In peritumoral areas, fibroblasts-melanoma interactions mediated by ADAM9 generate matrix modifications and enhance proteolytic activities necessary for melanoma growth." (PMID 35558554, 2022). "Further studies demonstrated that ADAM9 in melanoma cells is required to cleave the laminin beta 3 chain necessary to invade basement membranes and metastasis." (PMID 35558554, 2022). "In previous studies, circ-ADAM9 was discovered to be involved in regulating melanoma malignant progression." (PMID 35096421, 2022). "Another study also reported hsa-miR-126 downregulation contributes to dabrafenib acquired resistance in melanoma by upregulating ADAM9 and VEGF-A." (PMID 33880366, 2021). "A disintegrin and metalloproteinase domain-containing protein 9 (ADAM9) is expressed in human melanoma at the tumor-stroma border, where direct or indirect interactions between tumor cells and fibroblasts occur." (PMID 34360915, 2021). "ADAM-9 is a proteolytic and adhesive protein that allows cell–cell contacts between fibroblasts and melanoma cells." (PMID 34067929, 2021). "The strong expression of ADAM9 in the melanoma anterior margin and stromal cells near the tumor indicates that the tumor-stromal interaction promotes the induction of ADAM9 in vivo." (PMID 32875951, 2020). "The cell–cell adhesion of fibroblasts and melanoma cells is significantly reduced when incubated with the recombinant tandem disintegrin and cysteine-rich domains of ADAM9." (PMID 33096780, 2020). "Conversely, collagen type I expression was moderately, but not significantly, decreased at the transcriptional level, and the protein increased in ADAM9−/− fibroblast mono- and co-cultures with melanoma media." (PMID 32906814, 2020). "In melanoma tissues, ADAM9 protein is strongly expressed in tumor cells of the surrounding dermis and stromal cells adjacent to the leading edge of the tumor." (PMID 32875951, 2020). "This study aimed to dissect the structural modifications in the tumor microenvironment due to the stromal expression of ADAM9 during melanoma progression." (PMID 32906814, 2020). "We previously showed that the host deletion of ADAM9 leads to enhanced growth of grafted B16F1 melanoma cells by a mechanism mediated by TIMP1 and the TNF-α/sTNFR1 pathway." (PMID 32906814, 2020). "Among these enzymes, ADAM9 was up-regulated in human melanoma, but its function in this context was unclear." (PMID 32906814, 2020). "We observed increased collagen type I at the tumor–stroma border of melanomas from ADAM9−/− animals, which results from altered fibroblast activities." (PMID 32906814, 2020). "The abundance of ADAM9 RNA measured by RT-PCR is decreasedin vitro in human melanoma cells after culture with collagen type I or with Interleukin 1 alpha (IL1α) compared to mock stimulated conditions." (PMID 27990250, 2015). "In melanoma and a hepatic metastatic site of colon cancer, ADAM9 expression was upregulated at the invasion front, again supporting its role in tumor progression." (PMID 25177692, 2014). "These microRNAs play a tumour suppressor role in human melanoma through down-modulation of two metalloproteinases, ADAM9 and MMP7, resulting in decreased HB-EGF activation." (PMID 24990570, 2014). "In melanoma ADAM9 protein expression is restricted to the cells within the invading front, being detectable in tumor cells and in peritumoral stromal fibroblasts, and absent in fibroblasts distal to the tumor site." (PMID 23437250, 2013).
melanoma (continued). "Moreover, circ-ADAM9 was found to enhance the proliferation and glycolysis of melanoma cells by upregulating KLF3 through sponging miR-31." (PMID 35096421, 2022). "Furthermore, knockdown of miR-126-3p contributed to dabrafenib-acquired resistance in melanoma by elevating ADAM9 and VEGF-A." (PMID 34872448, 2021). "Furthermore, ADAM-9 ablation in fibroblasts has been shown to strongly inhibit both cell–cell adhesion and melanoma cell invasion in vitro." (PMID 34067929, 2021). "By grafting of ADAM9 expressing B16F1 melanoma cells in animals carrying complete ablation of this protease, we could show that in vivo ablation of this protease in stromal fibroblasts leads to enhanced tumor growth as a result of altered cellular activities." (PMID 32906814, 2020). "In contrast, ADAM9 mRNA cannot be detected in normal skin, meaning that the expression of ADAM9 in melanoma and stromal cells may be controlled by changes in related cells during tumor progression." (PMID 32875951, 2020). "Strategies restoring miR-126-3p expression or targeting VEGF-A or ADAM9 could restrain growth and metastasis of dabrafenib-resistant melanomas and increase their drug sensitivity." (PMID 31227006, 2019). "In this report, we showed that miR-126-3p was able to down-regulate ADAM9 protein levels also in dabrafenib-resistant melanoma cells, and that this molecular event was involved in the biological effects produced in the resistant cells by restoration of miR-126-3p expression." (PMID 31227006, 2019). "Furthermore, ADAM9 disintegrin domain mediates the interaction of fibroblasts and melanoma cells contributing to proteolytic activities required during invasion of melanoma cells." (PMID 28260841, 2017). "Human ADAM9 protein mediates cell-cell contact interaction between stromal fibroblasts and melanoma cells at the tumor-stroma border, thus contributing to proteolytic activities required during invasion of melanoma cells." (PMID 27990250, 2015). "In melanoma, ADAM9 is up-regulated in vivo at the invasion front." (PMID 18582378, 2008). "ADAM9 overexpression was reported in several human carcinomas, including oral, lung, breast, stomach, liver, pancreas, colon, kidney, prostate, cervix, and melanoma, and is correlated with cancer progression and metastasis, as well as having a predictive capacity for patient survival times." (PMID 25177692, 2014). "ECM-degrading proteases, including disintegrin and metalloprotease-9 (ADAM-9), MMP-2, -7, and -9, play pivotal roles in cancer processes, including the growth, migration, invasion, adhesion, proliferation, and apoptosis of melanoma." (PMID 38791435, 2024). "The plasma and expression levels of MMP-7 and -9 and ADAM-9 are reduced by AC-EO treatment in B16F10-injected mice and in B16F10 melanoma." (PMID 38791435, 2024). "ADAM-9 also induces cell signalling leading to increased secretion of the proteolytic enzymes MMP-1 and MMP-2 in fibroblasts and MMP-2 in melanoma cells." (PMID 34067929, 2021). "The extracellular matrix (ECM)-degrading proteases comprising a disintegrin and metalloprotease-9 (ADAM9), matrix metalloproteinase-7 (MMP7), and MMP9 play a pivotal role during melanoma growth, migration, and adhesion." (PMID 34360915, 2021). "In these cells, altered expression of ADAM9 controls TIMP-1 expression and TNF-α/sTNFR1 pathway leads to modulation of melanoma cells proliferation and apoptosis." (PMID 32906814, 2020). "ADAM9, a member of the ADAM family, is widely expressed and is up-regulated in several human cancers such as breast, prostate cancer, and melanoma." (PMID 32906814, 2020). "To evaluate the role of ADAM9 in the modification of the ECM during melanoma development, we have analyzed the ECM at the tumor-stroma border in B16F1 melanomas developed in wild type or ADAM9−/− mice." (PMID 32906814, 2020). "Melanoma cells were incubated with 100 nM dabrafenib (+) or with DMSO alone (-) and after 48 h ADAM9 expression was evaluated by immunoblotting." (PMID 31227006, 2019).